BRAF (B-Raf proto-oncogene, serine/threonine kinase)
Diseases named in the same sentence as BRAF in open-access papers (continued):
Sharing a sentence is not in itself a finding about the gene and the disease.
colorectal cancer (continued). "The role of the BRAF mutation in colorectal cancer and ATC underscores its importance as a potential target for therapeutic intervention." (PMID 40004697, 2025). "There is certainly an argument for large clinicopathologic–molecular studies of patients with colorectal cancer with class 2 or 3 BRAF mutations." (PMID 39751654, 2025). "Overall, 60 studies were eligible for inclusion: 25 single arm clinical trials, 28 controlled clinical trials, and seven multicentre real world studies, comprising 4633 patients with advanced BRAF-mutated colorectal cancer." (PMID 41355781, 2025). "Collectively, our study found that dual target inhibition of EGFR/BRAF drives the core antitumor activity in BRAF-mutated colorectal cancers." (PMID 41355781, 2025). "BRAF mutations are one of the most common oncogenic mutations, occurring in approximately 10% of colorectal cancers." (PMID 41002577, 2025). "In particular, Elez and collaborators demonstrated that inactivating RNF43 mutations are predictive of response to anti-BRAF drugs in microsatellite-stable (MSS) colorectal cancer patients." (PMID 40735046, 2025). "While this study provides significant insights into the epigenetic regulation associated with the BRAF-V600E mutation in colorectal cancer, several limitations warrant consideration." (PMID 40678543, 2025). "Our previous retrospective observational study revealed that BRAF V600E mutated colorectal cancer patients with and liver metastases had poorer prognosis and inferior treatment response." (PMID 41225509, 2025). "A recent study demonstrated that the BRAF mutation significantly enhances cytotoxic T cell infiltration in the tumor microenvironment of colorectal cancer, indicating its potential as a favorable factor for immunotherapy." (PMID 39934467, 2025). "Unlike other cancers with a high prevalence of V600EBRAF mutations, colorectal cancers with V600EBRAF mutations are resistant to BRAF inhibitor monotherapy treatment." (PMID 41002577, 2025). "Our findings established the anti-EGFR/BRAF based regimen as optimal strategy for patients with BRAF-mutated colorectal cancer in both first line and second line settings." (PMID 41355781, 2025). "There is significant heterogeneity in presentation, behaviour and outcomes in patients with BRAF-mutated colorectal cancer." (PMID 41002577, 2025). "Our review investigated a targeted therapy strategy for advanced BRAF-mutated colorectal cancer in a large population, comprising 4633 patients, providing comparative analyses of 12 first line regimens and 14 second line regimens." (PMID 41355781, 2025). "BRAF mutation is a key driver mutation in the development and progression of various cancers, including melanoma, colorectal cancer (CRC), non-small cell lung cancer (NSCLC), and others." (PMID 39934467, 2025). "In one study, among the seven most common KRAS mutations, the c.35G>T (p.G12V) mutation was associated with significantly higher colorectal cancer-specific mortality compared to KRAS wild-type/BRAF wild-type cases." (PMID 40282985, 2025). "Several studies regarding patients with colorectal cancer with BRAF mutation have found Bevacizumab therapy with chemotherapy to be quite successful, improving overall survival compared to patients just undergoing chemotherapy alone." (PMID 40943615, 2025). "On the other hand, microsatellite stable BRAF mutant colorectal cancers are particularly aggressive, yet the mutation also increases responsiveness to EGFR inhibitor therapy." (PMID 41310156, 2025). "A small group of parental cells already had pre-existing amplification of BRAF, which was also found in some BRAF-mutated colorectal cancer cells." (PMID 40872623, 2025). "The most common BRAF driver mutation in colorectal cancer is a valine to glutamic acid substitution, V600E, that causes constitutive Ras pathway activation downstream of BRAF." (PMID 39751654, 2025).
colorectal cancer (continued). "This pathway is known to be implicated in the pathophysiology of colorectal cancer with the BRAF V600E mutation." (PMID 41234433, 2025). "This real-world study aims to describe the molecular profile, clinical phenotype, and patient outcomes of BRAF-mutated colorectal cancer treated at a single tertiary referral cancer centre in the United Kingdom." (PMID 41002577, 2025). "A recent study from Australia suggested a significantly higher incidence of BRAF V600E mutations among patients with colorectal cancer and age 40 or below." (PMID 40940860, 2025). "In this study, we explored the prognostic impacts of HIF-1α, LOX and ITGA5 expression in the tumor microenvironment and their relationship with KRAS/NRAS/BRAF mutation status in colorectal cancers." (PMID 39857068, 2025). "Class I BRAF mutations are frequently found in patients with non-BRAF dependent lung and colorectal cancer resistant to EGFR inhibitors." (PMID 40977811, 2025). "Thirty studies investigated second or later line therapies for advanced BRAF-mutated colorectal cancer in a pooled population of 2173 patients." (PMID 41355781, 2025). "The combination of cetuximab (an EGFR inhibitor) and encorafenib (a BRAF inhibitor) has been approved for treating BRAF-mutated colorectal cancer in the U.S. and Europe." (PMID 39757310, 2025). "In colorectal cancer, BRAF mutations also predict failure of the epidermal growth factor receptor inhibitors cetuximab and panitumumab and are associated with shorter overall and progression-free survival." (PMID 41440935, 2025). "There is significant heterogeneity in cancer behaviour and clinical outcomes amongst patients with BRAF-mutated colorectal cancer." (PMID 41002577, 2025). "The BRAF V600E mutation is found in approximately 10% of colorectal cancer cases and 25–45% of ATC cases." (PMID 40004697, 2025). "The IC50 values for ML varied between the three cell lines, with the most potent effect observed in BRAF-mutated HT-29 colorectal cancer cells, followed by the BRAF-mutated 8305C and then Caco-2 cells." (PMID 40004697, 2025). "Clinically, colorectal cancer in elderly patients often shows distinct molecular features, including higher rates of microsatellite instability and BRAF mutations, which have important therapeutic implications." (PMID 41373662, 2025). "Using multiple meta-analysis approaches, we found that anti-EGFR/BRAF based regimens represent an optimal therapeutic strategy for patients with advanced BRAF-mutated colorectal cancer." (PMID 41355781, 2025). "Mutations in BRAF, particularly the V600E variant, are frequently observed in colorectal cancer (CRC) and are associated with poor prognosis and therapeutic challenges." (PMID 40942081, 2025). "This work proposes a new mechanistic link between BRAF mutations and hypermethylation, inspiring further work on the role of vitamin C in the genesis of BRAF-mutated colorectal cancer." (PMID 40102611, 2025). "It has been recognized for 15 or more years that colorectal cancer with a BRAF-V600E mutation, present in about 10%-12% of metastatic colorectal cancers, is a particularly aggressive and difficult-to-treat tumor." (PMID 41056448, 2025). "In our cohort, 30% of patients tested had a co-existing RNF43 mutation, which is consistent with previously reported prevalences in patients with BRAF-mutated colorectal cancers." (PMID 41002577, 2025). "In advanced colorectal cancer, BRAF-mutated CRC represents a distinct clinical entity characterized by specific patient demographics, clinical behavior, and prognostic outcomes." (PMID 40332392, 2025). "Of the 31 (31/6605, 0.47%) colorectal cancers with class 2 BRAF mutations (codons 464, 469, 597, and 601), nine had additional pathogenic Ras pathway mutations (9/31, 29.0%)." (PMID 39751654, 2025). "Colorectal cancers with high-level miR21 expression frequently harbor BRAF mutations and a CpG island methylator phenotype-high, which showed a significant link to the SSL series." (PMID 40693022, 2025).
colorectal cancer (continued). "The association between BRAF p.V600E mutation and colorectal cancer-specific death changed from 1.96 (P = 2 × 10− 10) to 1.70 (P = 5 × 10− 06) after adjusting for stage." (PMID 41413856, 2025). "Considering the significant serine phosphorylation modification at position 1579 on KIAA1429, we then screened out four potential serine kinases, including BRAF, a well-known mutated kinase in colorectal cancer." (PMID 40611274, 2025). "The associations of IDH1/2 mutations with older age and the BRAF p.V600E substitution have been described in colorectal cancer." (PMID 41413856, 2025). "Focusing on the 37 colorectal cancers with class 3 BRAF mutants and concomitant Ras pathway mutations, only eight harbored typical KRAS mutations (P < 10−5, Fisher exact test)." (PMID 39751654, 2025). "Of the 60 included studies, 32 focused on first line therapy in 2460 patients with advanced BRAF-mutated colorectal cancer." (PMID 41355781, 2025). "In colorectal cancer, the BRAF V600E mutation is associated with chemoresistance, and an overall dismal prognosis." (PMID 40004697, 2025). "Our study demonstrates for the first time that the BRAF V600E mutation significantly elevates IDO1 expression in colorectal cancer." (PMID 39934467, 2025). "This study provides significant insights into the structural dynamics of BRAF variants and their relationship to drug resistance in colorectal cancer, using molecular dynamics simulations and machine learning techniques." (PMID 40942081, 2025). "The role of genetic mutations, particularly those affecting oncogenes like BRAF, and the development of drug resistance continue to be central challenges in colorectal cancer treatment." (PMID 40942081, 2025). "BRAF mutations, present in 4.5–6.7% of Japanese patients with colorectal cancer (CRC), are associated with poor survival in advanced and recurrent CRC." (PMID 40890837, 2025). "We characterized the metabolomic, epigenetic and transcriptomic patterns of altogether 39 microsatellite stable BRAF-mutated colorectal cancers." (PMID 40102611, 2025). "Somatic mutations in the BRAF gene occur in a variety of human cancers including melanoma and colorectal cancer (CRC)." (PMID 40102611, 2025). "In summary, our findings shed further light on the classes of atypical BRAF mutations in colorectal cancer, which differ both molecularly and pathologically from typical BRAF-mutant disease." (PMID 39751654, 2025). "Anti-EGFR/BRAF regimens outperformed other targeted combinations in pretreated patients, reinforcing that EGFR and BRAF are pivotal therapeutic targets for BRAF-mutated colorectal cancer." (PMID 41355781, 2025). "As a result, only the doublet regimen has received FDA approval, while the triplet combination has been approved in Japan for use in patients with various BRAF-mutated colorectal cancers." (PMID 40688855, 2025). "BRAF-mutated colorectal cancer is an aggressive entity related with poor prognoses and limited data in Latin America, reflecting gaps in research and practice." (PMID 40149341, 2025). "Colorectal cancer is commonly treated with chemotherapy, but when certain genetic variations, such as BRAF mutations, are present, targeted therapies are incorporated into the treatment strategy." (PMID 40942081, 2025). "The results of these analyses demonstrated that BRAF V600E mutation significantly alters the immune-related characteristics of colorectal cancer, providing a foundation for our further studies." (PMID 39934467, 2025). "The serrated pathway in colorectal cancer is characterized by early BRAF V600E mutations, which activate the MAPK-ERK pathway and drive tumor progression." (PMID 41170468, 2025). "Owing to the limited efficacy of conventional therapeutic strategies for BRAF-mutated colorectal cancer, BRAF targeted therapies have been explored to improve therapeutic efficacy." (PMID 41355781, 2025).
colorectal cancer (continued). "Microsatellite instability high (MSI-H) and mismatch repair deficient status are more common in BRAF-mutated colorectal cancer." (PMID 41002577, 2025). "Implications: The heterogeneous nature of BRAF-mutant colorectal cancers, particularly among class 2/3 mutations which frequently harbor additional Ras mutations, highlights the necessity of comprehensive molecular profiling." (PMID 39751654, 2025). "We then assessed the 81 (81/6605, 1.22%) colorectal cancers with a class 3 BRAF mutation (codons 466, 581, 594, 595, and 596)." (PMID 39751654, 2025). "This study successfully combined molecular dynamics simulations with machine learning to predict the drug resistance of BRAF variants to dabrafenib and vemurafenib in colorectal cancer." (PMID 40942081, 2025). "Among individual genes, only the BRAF p.V600E mutation was significantly associated with DS-survival, suggesting a limited survival impact from mutations driving colorectal cancer development." (PMID 41413856, 2025). "Clinical trials and multicentre, real world studies investigating the efficacy and safety of targeted therapies for advanced BRAF-mutated colorectal cancer with at least one of the clinical outcomes of interest." (PMID 41355781, 2025). "Colorectal cancer is a common disease, and a specific genetic change called a BRAF mutation is often used by doctors to guide treatment decisions." (PMID 41002577, 2025). "Previous meta-analyses investigating first line therapies for BRAF-mutated colorectal cancer have provided limited insights." (PMID 41355781, 2025). "This systematic review comprehensively summarised the efficacy and safety of currently available targeted therapy strategies for advanced BRAF-mutated colorectal cancer." (PMID 41355781, 2025). "For example, colorectal cancers with class 1 BRAF mutations are likely to be CMS1, whereas class 3 mutants are rarely CMS1 and class 2 mutants fall into either group." (PMID 39751654, 2025). "Previous studies have validated the efficacy of CT-based radiomic models in predicting KRAS, NRAS, and BRAF mutations in colorectal cancer." (PMID 41409606, 2025). "Overall, our data suggest a progressive de-escalation of chemotherapy’s role across treatment lines among patients with advanced BRAF-mutated colorectal cancer, highlighting implications for the design of future trials." (PMID 41355781, 2025). "BRAF mutations in colorectal cancer comprise three functional classes: class 1 (V600E) with strong constitutive activation, class 2 with pathogenic kinase activity lower than that of class 1, and class 3 which paradoxically lacks kinase activity." (PMID 39751654, 2025). "Machine learning Elastic-net allowed us to build a mixed metabolism/mitochondria activity score, which was found to be an independent parameter predictive of BRAF-V600E mutation status in colorectal cancer." (PMID 41440935, 2025). "Oncogenic codon V600E mutations of the BRAF gene affect 10–15% of colorectal cancers, resulting in activation of the MAPK/ERK signaling pathway and increased cell proliferation and survival." (PMID 40102611, 2025). "This suggests that BRAF V600E mutation influences TME patterns in colorectal cancer, acting as a favorable factor for immune infiltration." (PMID 39934467, 2025). "While clinical data on this triplet therapy in BTC remain limited to case reports, it has shown promising efficacy in BRAF V600E-mutated colorectal cancer." (PMID 40688855, 2025). "It is worth mentioning, however, that MSI/MMRd colorectal carcinomas and MSI/MMRd EC show molecular differences with respect to the level of instability and the co-existence between MSI/MMRd and BRAF V600E mutations in colorectal carcinomas." (PMID 40468018, 2025). "The association between TLS and mutations in the PI3K‐mTOR pathway in renal clear cell carcinoma, BRAF mutations in colorectal carcinoma, and APC germline mutations in hepatoblastoma has been reported in studies." (PMID 40396416, 2025).
colorectal cancer (continued). "This suggests that the genetic profile of rectal cancers in this dataset differs significantly from right-sided colorectal cancers, which often exhibit BRAF mutations." (PMID 39768914, 2024). "The study employed the TruSight Tumor 15 next-generation sequencing (NGS) panel on 86 colorectal cancer (CRC) samples to detect somatic mutations in BRAF, KRAS, and NRAS genes." (PMID 39635441, 2024). "The survival rate for individuals with metastatic MSI colorectal cancers who have BRAF mutations is, however, rather low." (PMID 39031216, 2024). "The majority of patients (65.6%, n = 82/125) had a node-positive index colorectal cancer, while the pathology showed mucinous type adenocarcinoma in 28% (n = 35/125), and 8% (n = 10/125) were BRAF mutated." (PMID 39057141, 2024). "BRAF mutations, which are predominantly found in right-sided colorectal cancers, are linked to poor prognostic outcomes and require targeted therapeutic approaches." (PMID 39768914, 2024). "The rare S607T substitution was previously reported in a unique case of colorectal cancer and its pathogenic role is uncertain, whereas BRAF V600E is a canonical driver event of tumorigenesis." (PMID 39018206, 2024). "The combination therapy of binimetinib, encorafenib, and cetuximab ("triplet regimen") was approved in Japan in November 2020 for the second-line treatment of BRAF V600E mutation-positive colorectal cancer." (PMID 39310595, 2024). "Serine/threonine-protein kinase B-raf (BRAF) mutations are found in 8-15% of colorectal cancer patients and identify a subset of tumors with poor outcome in the metastatic setting." (PMID 38348572, 2024). "With appropriate dose reduction and attention to side effects, this regimen is considered feasible for the long-term treatment of BRAF V600E mutation-positive advanced recurrent colorectal cancer in patients aged >70 years." (PMID 38741697, 2024). "In colorectal cancer patients, BRAF mutations account for approximately 4%–12% of all colorectal cancer cases, and about 90% of these mutations are V600E mutations." (PMID 39529955, 2024). "Multiple driver genes of relatively high prevalence in other cancer types were associated with race, including an increased frequency of KRAS and PTEN mutations but decreased prevalence of APC and BRAF mutations in Black patients with colorectal cancer." (PMID 38297963, 2024). "BRAF mutation-positive colorectal cancers have also been shown to have increased PD-L1 expression, suggesting that the MAPK pathway is involved in the regulation of CD274 expression in the intestinal epithelium." (PMID 38920700, 2024). "The clinical and pathological information of 206 patients with BRAF V600E-mutated colorectal cancer diagnosed in Cancer Hospital, Chinese Academy of Medical Sciences, and Peking Union Medical College from 2014 to 2021 was retrospectively collected." (PMID 39464719, 2024). "Testing for RAS and BRAF mutations at the time of colorectal cancer diagnosis is crucial because it helps to determine the appropriate chemotherapy regimen." (PMID 38608071, 2024). "The presence of a BRAF mutation is indicative of sporadic multiple sclerosis of the colon (MSI) colorectal cancer and, in essence, eliminates the possibility of a Lynch syndrome diagnosis." (PMID 39031216, 2024). "BRAF mutations are found in approximately 10% of metastatic colorectal cancer (mCRC) and up to 20% of colorectal cancer overall." (PMID 38203795, 2024). "Nevertheless, ongoing clinical trials are exploring novel treatment approaches for BRAF-mutated colorectal cancer, including combinations of targeted therapies, immunotherapies, and chemotherapy." (PMID 39273409, 2024). "We evaluated patients with a BRAF mutated colorectal cancer treated with FTD–TPI as part of routine hospital care." (PMID 39766040, 2024).